ATG4B (autophagy related 4B cysteine peptidase)
Diseases named in the same sentence as ATG4B in open-access papers (continued):
Sharing a sentence is not in itself a finding about the gene and the disease.
neurodegenerative disease (3 papers, 2017 to 2024). A disorder of the central nervous system characterized by gradual and progressive loss of neural tissue and neurologic function. "This is crucial as it underlines the role of ATG4B in maintaining cellular homeostasis and its potential implication in the progression of neurodegenerative diseases." (PMID 39305312, 2024). "Since autophagy is also associated with neurodegenerative diseases, we tested whether Atg4b overexpression specifically in the Drosophila nervous system also improves lifespan." (PMID 37373039, 2023). "Taken together, our results revealed an important link between ATG4 factors and healthspan and lifespan, and offered ATG4, in particular ATG4D and ATG4B, as potential target for intervention of neurodegenerative diseases." (PMID 37373039, 2023). "The correction of ATG4B cryptic splicing in human cells shown in a dose-dependent manner in this study has the potential to become a treatment across multiple patient populations with neurodegenerative diseases." (PMID 39305312, 2024). "Therefore, regulating the intrinsic anti-oxidant capacity and normalizing ATG4B and p62/SQSTM1 and other ubiquitin adapter proteins will be important for maintaining a normal level of mitophagy flux and bioenergetics for cell survival in chronic nutrient access and neurodegenerative diseases." (PMID 28492550, 2017).
hematological malignancies (1 paper, 2025). "Overall, targeting ATG4B has mild effects on hematopoietic cells, including T cells, which supports the utility of ATG4B as a suitable therapeutic target for hematological malignancies." (PMID 41275290, 2025).
ATG4B also shares sentences with these, for which no sentence is quoted: breast tumor (2 papers); triple-negative breast carcinoma (2); chronic obstructive pulmonary disease (1); colorectal tumors (1); gynecologic tumor (1); Hepatic steatosis (1); Huntington disease (1); infectious disease (1); Insulin resistance (1); ischemia (1); Lewis lung carcinoma (1); lymphoma (1); metastatic disease (1); Oral Squamous Cell Carcinoma (1); proteinopathies (1); renal carcinoma (1); type-I diabetes (1).